GABRA1 (gamma-aminobutyric acid type A receptor subunit alpha1)
Diseases named in the same sentence as GABRA1 in open-access papers (continued):
Sharing a sentence is not in itself a finding about the gene and the disease.
depression (5 papers, 2017 to 2025). "In another study significant GABA-A expression differences between depressed and non-depressed suicide victims were found in all limbic regions pointing to GABA dysfunction in the limbic system in depression and suicide, especially GABRA1 and GABRB148." (PMID 29018204, 2017). "The docking results of GABRA1 with naringenin and hesperidin, HCRTR1 with naringenin-7-O-glucoside, poncirenin and genipin 1-gentiobioside, and luteolin with SLC6A4, GLO1, MAOB and MTNR1A may clarify the mechanism of action of ZZHPD in treating insomnia and depression." (PMID 35095537, 2021).
insomnia (5 papers, 2007 to 2024). A sleep disorder characterized by difficulty in falling asleep and/or remaining asleep. "Amongst the various subunits of the GABAA receptor family implicated in insomnia mediation are frequently reported ones such as GABRA1 and GABRG2." (PMID 38463787, 2024). "GABA antagonists such as zopiclone, used to treat insomnia, are of potential benefit to GABRA1-related excitotoxicity." (PMID 17244347, 2007). "GABAARα1 (GABRA1) and GABAARγ2 (GABRG2) are two significant subunits of GABA receptors, and are known to play an important role in the first line treatment of insomnia." (PMID 35002696, 2021). "Of the GABAA receptor subunits, GABRA1 and GABRG2 have been frequently reported to mediate insomnia." (PMID 35002696, 2021). "In this study, RT-qPCR and immunohistochemistry revealed that an extract of ZSS led to an increase in the expression of GABRA1 and GABRG2 receptors in the hypothalamus of rats suffering from insomnia." (PMID 35002696, 2021). "GABRA1 and GABRA2 are the components of the heteropentameric receptor for GABA, receptor of GABA (gamma-aminobutyric acid) that is an important inhibitory neurotransmitter in vertebrate brain and plays an essential role in the treatment of insomnia by inhibiting brain neurotransmitters excitement." (PMID 30891080, 2019).
schizophrenia (5 papers, 2011 to 2021). A major psychotic disorder characterized by abnormalities in the perception or expression of reality. "GABRA1 mRNA was 43.77% lower in the midbrain of schizophrenia cases compared with controls (U = 156.0; p < 0.0001)." (PMID 34174930, 2021). "We sought to determine relative levels of GABRA1, GABRA2, GABRA3, and GABRA5 mRNAs, GABRA3 protein levels, and to determine cellular location of GABRA3 protein in the midbrain in schizophrenia." (PMID 34174930, 2021). "Furthermore, the dissimilarities between the symptoms of schizophrenia and those observed so far in the Gabra1 and Gabra5 knockouts suggest that the extensive similarities between Gabrb2 knockout and schizophrenia are not readily shared by knockouts of other subunits of GABAA receptors." (PMID 30013074, 2018).
alcohol dependence (4 papers, 2005 to 2022). Physical and psychological dependence on alcohol. "Even protection from alcohol dependence has been attributed to GABRA1 and GABRA2 polymorphisms in a small study from India, probably due to ethnic stratification effects." (PMID 36422192, 2022). "Among these genes, GABRA1 is a member of the same gene family with GABRA2 that was recently reported as alcoholism susceptibility gene." (PMID 16451705, 2005). "Of note, GABRA1 is a member of the same gene family as GABRA2, which was reported recently to be associated with alcoholism." (PMID 16451705, 2005).
childhood absence epilepsy (4 papers, 2016 to 2025). A familial generalized pediatric epilepsy, characterized by very frequent (multiple per day) absence seizures, usually occurring in children between the ages of 4 and 10 years, with, in most cases, a good prognosis. "In another case, a patient diagnosed with childhood absence epilepsy (CAE) harbored the de novo GABRA1 frameshift variant, S326fs, yet responded well to treatment with valproate, an anti-seizure drug." (PMID 39651292, 2025).
cognitive deficits (4 papers, 2016 to 2025). "For instance, PTGS2, MAPT, and GABRA1 are critical targets of leukodystrophy and are associated with AD, neuropathic pain, and cognitive impairment in the T-D network." (PMID 36500385, 2022). "Taken together, we hypothesize that JWH 133 administration rescues the expression of GABRA1 due to suppressed reactive astrocytes, and this promotes the amelioration of cognitive deficits." (PMID 39587077, 2024).
developmental delay (4 papers, 2018 to 2025). "This patient also exhibited severe developmental delay; however, it remains unclear whether delay stems from the GABRA1 variant or the patient’s coexisting condition, Williams-Beuren syndrome (WBS)." (PMID 39651292, 2025). "We have recently identified a novel de novo T292S (C875G) missense variant of GABRA1 from a pediatric patient with developmental delay, but, to our surprise, without diagnosed seizure events." (PMID 35269865, 2022). "We have identified a novel de novo T292S missense variant of GABRA1 from a pediatric patient with grievous global developmental delay but without obvious epileptic activity." (PMID 35269865, 2022).
temporal lobe epilepsy (4 papers, 2011 to 2024). A localization-related (focal) form of epilepsy characterized by recurrent seizures that arise from foci within the temporal lobe, most commonly from its mesial aspect. "Limited to patients with temporal lobe epilepsy, we detected a significant correlation between the exponent and the cortical expression of GABRA1, GRIN2A, GABRD, GABRG2, KCNA2 and PDYN genes." (PMID 39056027, 2024).
West syndrome (4 papers, 2018 to 2024). "No patient with neurological disorders was found in the high increase group, whereas three cases (West syndrome, X linked lissencephaly, GABRA1/EIEE-19) were observed in the group with a medium increase of atBCs." (PMID 35722474, 2022). "In combination with previous studies, we found that the West syndrome phenotype of the GABRA1 pathogenicity variants focuses on the amino acid changes at position 257–263." (PMID 35937053, 2022).
Alzheimer disease (3 papers, 2021 to 2024). A progressive, neurodegenerative disease characterized by loss of function and death of nerve cells in several areas of the brain leading to loss of cognitive function such as memory and language. "Additionally, neuron cells including inhibitory neuron, and excitatory neuron in Alzheimer’s disease displayed downregulated GABRA1 expression and upregulated CD59, a complement regulatory protein, indicating increased complement activation." (PMID 39897171, 2024).
epilepsy syndrome (3 papers, 2021 to 2024). A syndrome that has a characteristic cluster of clinical features and/or lectroencephalographic (EEG) findings that reflect underlying epileptic activity. "Among the common GABR genes with widespread distribution in the CNS and association with inherited epilepsy syndromes are GABRA1, GABRB2 and GABRG2." (PMID 34095830, 2021). "Accumulated evidence indicated that mutations in GABRA1 contribute to the genetic etiology of both benign and severe epilepsy syndromes." (PMID 34029007, 2021).
absence seizure (2 papers, 2019 to 2021). "In clinical research, a mutation of GABRA1 was observed in children with absence seizure." (PMID 34029007, 2021).
breast carcinoma (2 papers, 2023 to 2025). "We found that the seven GABAA receptor subunits were upregulated in TNBC breast cancers, including GABRA1, GABRA5, GABRD, GABRE, GABRP, GABRQ, and GABRG3." (PMID 36923530, 2023).
glioblastoma (2 papers, 2021 to 2025). The most malignant astrocytic tumor (WHO grade IV). "D'Urso’s study indicated a lack of GABRA1 mRNA expression in glioblastoma primary cultures via northern blot and immunohistochemical analysis." (PMID 34001135, 2021).
Influenza infection (2 papers, 2023 to 2025). "Gabra1-ABLATE mice displayed attenuated sickness responses to influenza infection that were similar to those in Gabra1-IRES-cre; Ptger3flox mice or ibuprofen-treated mice." (PMID 36890237, 2023). "Of note, the kinetics of residual sickness behaviour following manipulation of petrosal GABRA1 neurons matches the time course of virus accumulation in the lungs, indicating that there are probably two phases of influenza-induced sickness behaviour." (PMID 36890237, 2023). "Ablating petrosal GABRA1 neurons or targeted knockout of PGE2 receptor 3 (EP3) in these neurons eliminates influenza-induced decreases in food intake, water intake and mobility during early-stage infection and improves survival." (PMID 36890237, 2023). "Here, using genetic tools that broadly cover a peripheral sensory neuron atlas, we instead identified a small population of PGE2-detecting glossopharyngeal sensory neurons (petrosal GABRA1 neurons) that are essential for influenza-induced sickness behaviour in mice." (PMID 36890237, 2023). "Thus, deletion of the EP3 receptor in a small subset of Gabra1-expressing peripheral sensory neurons (NP9 neurons) has a wide-ranging effect on behavioural responses to influenza infection." (PMID 36890237, 2023). "Gabra1-IRES-cre; Ptger3flox mice additionally displayed an attenuated hypothermia response to influenza infection." (PMID 36890237, 2023). "GABA A receptor 1 (GABRA1) in the cell bodies of the glossopharyngeal nerve, which projects to the nasopharynx, senses secreted PGE2 through the PGE2 receptor 3 (EP3) following influenza infection." (PMID 39958365, 2025). "However, influenza-induced sickness behaviour was normal in Trpv1-IRES-cre; Ptger3flox mice, and furthermore, GABRA1 neurons are predominantly Trpv1-negative." (PMID 36890237, 2023). "Influenza infection induced PGE2 to similar levels in plasma and BALF of Gabra1-IRES-cre; Ptger3flox, Phox2b-cre; Ptger3flox, Advillin-creER; Ptger3flox and Ptger3flox mice, consistent with changes in PGE2 detection rather than PGE2 synthesis underlying the observed behavioural differences." (PMID 36890237, 2023). "We used a complementary approach involving diphtheria toxin-guided cell ablation to clarify a role for Gabra1-expressing vagal–glossopharyngeal sensory neurons in influenza-induced sickness, and rule out a role for other Gabra1 expression sites." (PMID 36890237, 2023). "Through the ablation of GABRA1+ neurons or deletion of EP3 receptors in these neurons, symptoms of reduced food and water intake and impaired exercise capacity during early influenza infection can be eliminated, although allodynia or algesia was not measured in this study." (PMID 39958365, 2025).
osteoarthritis (2 papers, 2022). A noninflammatory degenerative joint disease occurring chiefly in older persons, characterized by degeneration of the articular cartilage, hypertrophy of bone at the margins and changes in the synovial membrane. "For instance, one recent study examined the role of the lncRNA Gm37494 in the context of osteoarthritis, focusing on its capability to target GABRA1 by binding to miR-181a-5p." (PMID 36497462, 2022).
Seizure (2 papers, 2013 to 2021). A seizure is an intermittent abnormality of nervous system physiology characterized by a transient occurrence of signs and/or symptoms due to abnormal excessive or synchronous neuronal activity in the brain. "MiR‐129–2‐3p level was significantly upregulated, whereas GABRA1 expression downregulated in KA‐treated rat primary hippocampal neurons and KA‐induced seizure model." (PMID 34029007, 2021).
alcohol-use disorder (1 paper, 2016). "Pafah1b1 has been shown to be co-expressed with GABA type-A receptor subunits (specifically Gabra1, Gabrb2, and Gabrg2), a family of neurochemical receptors associated with alcohol-use disorder." (PMID 26834590, 2016).
channelopathy (1 paper, 2022). Channelopathies are a group of diseases caused by the dysfunction of ion channel subunits or their interacting proteins. "The underlying channelopathy pathway accounted for 46.7% (7/15) of the monogenic variants, including ion channel genes (SCN1A, KCTD7, KCNC1, CACNA1A, KCNMA1) and ligand-gated ion channel genes (GABRA1, GABRG2)." (PMID 36034301, 2022).
chordoma (1 paper, 2023). Chordomas are rare malignant tumors arising from embryonic remnants of the notochord in axial skeleton. "Genes marked on the volcano plot were either implicated earlier in chordoma biology (e.g. keratins—KRT8, KRT18, KRT19, TBXT, LMX1A, and EGFR) or identified by outstanding p-value (e.g. IL11, CD24), high absolute fold-change (e.g. GABRA1) or DMR result (e.g. MNX1)." (PMID 37434245, 2023).
Cohen syndrome (1 paper, 2022). Cohen syndrome (CS) is a rare genetic developmental disorder characterized by microcephaly, characteristic facial features, hypotonia, non-progressive intellectual deficit, myopia and retinal dystrophy, neutropenia and truncal obesity. "The following genes were identified in 6 patients: cytogenetic band 6q21, PTRHD1, 22q11.23 deletion, Cohen syndrome, CTU2 gene, GABRA1 gene, and tuberous sclerosis." (PMID 35756865, 2022).
colitis (1 paper, 2025). Inflammation of the colon. "Activation of epithelial gamma-aminobutyric acid (GABA) A receptors α1 (encoded by Gabra1) worsens DSS colitis by inhibiting mucosal regeneration." (PMID 40791429, 2025).
colon cancer (1 paper, 2024). "However, irrespective of whether expression of GABAA or GABAB receptor subunits were altered in colon cancer, expression of particular receptor subtypes (GABRA1, GABRA5, GABRD, GABRE, GABRG1, GABRG3, GABBR1, and GABBR2) was significantly associated with poor clinical outcome." (PMID 38886975, 2024).
delirium (1 paper, 2023). A disorder characterized by confusion; inattentiveness; disorientation; illusions; hallucinations; agitation; and in some instances autonomic nervous system overactivity. "Fluctuations in core clinical features of DLB are typically delirium-like, occurring as spontaneous alterations in cognition, attention, and arousal, which is different from PDD; similarly, in our study, GABRA1 and GABRG2 genes were downregulated in DLB." (PMID 36970514, 2023).
developmental and epileptic encephalopathy, 19 (1 paper, 2023). Any early infantile epileptic encephalopathy in which the cause of the disease is a mutation in the GABRA1 gene. "GABRA1(+) - a heterozygous variant in exon 11 (c.1397C>T) associated with developmental and epileptic encephalopathy-19, an autosomal dominant disorder." (PMID 37519562, 2023).
Jeavons syndrome (1 paper, 2025).
mental disorder (1 paper, 2022). A disease that has its basis in the disruption of mental process. "The core targets of SHR during the treatment of mental disorders were GABRA1, GABRA2, GABRA3, GABRA5, and GABRA6, involving synaptic transmission and transmembrane movement." (PMID 39280954, 2022).
migraines (1 paper, 2025). "PTGS2, PTGS1, PPARG, ADRB2, GABRA1, and NOS3 are potential targets for the treatment of migraines using ginkgo seeds due to their advantageous values." (PMID 41009787, 2025).
nicotine addiction (1 paper, 2022). "Several switch genes, including GABRA1 and GABRD, were linked to nicotine addiction in M-AD." (PMID 36389068, 2022).
Osteochondrosis (1 paper, 2025). Abnormal growth ossification centers in children. "In the present study, among the genes nearby the associated SNP on chromosome 14, the genes GABRA1, GABRB2 and, especially, GABRA6 have previously been suggested to be associated with osteochondrosis in Standardbreds, and Hanoverian warmblood horses (GABRA6) (Naccache, Metzger, and Distl 2018)." (PMID 39754479, 2025).
rhinitis (1 paper, 2025). An inflammation of the mucous membrane lining the nose, usually associated with nasal discharge. "Many side-effects linked to GABRA1 are immune related: upper respiratory tract infection and neutrophil count, white blood cell count, and rhinitis." (PMID 40720497, 2025).
Tremor (1 paper, 2015). An unintentional, oscillating to-and-fro muscle movement about a joint axis. "In Gabra1 model of action tremor, knockout mice of α1 subunit of the γ-aminobutyric acid (GABA) receptor, additional knockout of α1G enhances action-induced tremor." (PMID 25588467, 2015).
upper respiratory infection (1 paper, 2023). "All such responses to infection would critically depend on the EP3 receptor in petrosal GABRA1 neurons, which serves an essential role in first relaying the presence of an upper respiratory infection to the brain, ultimately evoking sickness behaviour." (PMID 36890237, 2023).
cancer (5 papers, 2010 to 2025). A tumor composed of atypical neoplastic, often pleomorphic cells that invade other tissues. "The frequency of mutation in the GABRA6, GABRA1, and GABRB2 genes was significantly higher than that detected for other cell-cycle- and cell-proliferation-related genes; furthermore, their co-occurrence in patients with cancer was examined." (PMID 39695141, 2024).
tumor (5 papers, 2021 to 2025). "As expected, OPC markers OLIG2, SOX9, and cell cycle genes CDK1, MKI67 are highest in the tumor core (early peak), while neuronal markers ZIC1, GABRA1, and mature oligodendrocyte marker MBP are highest in the GCL_N (late peak)." (PMID 36823172, 2023). "Shared decreased protein-coding genes across all tumor types included FOXP2, GABRA1/2/4/5, NRGN, SST, and SYNPR." (PMID 36865335, 2023).
infection (4 papers, 2021 to 2024). The state of being infected such as from the introduction of a foreign agent such as serum, vaccine, antigenic substance or organism. "Genetically guided anatomical mapping revealed that petrosal GABRA1 neurons project to mucosal regions of the nasopharynx with increased expression of cyclooxygenase-2 after infection, and also display a specific axonal targeting pattern in the brainstem." (PMID 36890237, 2023). "Levels of interferon-gamma (IFNγ), TNF and interleukin 6 (IL-6) similarly peaked in BALF of control mice 5 days after infection, and were likewise decreased and delayed in Gabra1-IRES-cre; Ptger3flox mice." (PMID 36890237, 2023). "The significant drop in GABRA1 expression during the mid- and late chronic stage could be a major target for treatment of infection-induced neuropathology and chronic infection in the future." (PMID 33816350, 2021).
neurological disorders (3 papers, 2010 to 2023). "GABRA1 encodes for the α1 subunit of the GABAAR and to date, over 30 different variants in the GABRA1 gene have been reported and associated with neurological disorders and neurodevelopmental defects." (PMID 36747751, 2023).
genetic diseases (2 papers, 2022 to 2023). "A total of 25 GABRA1 mutations with explainable origins for the occurrence of genetic diseases have been identified in 47 patients (36 cases) so far, including two novel missense and the first frameshift mutation from the present study." (PMID 38269327, 2023).
metabolic disorders (1 paper, 2021).
respiratory diseases (1 paper, 2025). "The “active component–target–disease” network further demonstrated these essential oil components’ potential efficacy against pain, tumors, neuropsychiatric diseases, eye diseases, and respiratory diseases, which were highly related to PPARA, GABRA1, PTGS2, and SLC6A2." (PMID 40729010, 2025).